TPP1 (tripeptidyl peptidase 1)
Diseases named in the same sentence as TPP1 in open-access papers (continued):
Sharing a sentence is not in itself a finding about the gene and the disease.
osteosarcoma (1 paper, 2020). A usually aggressive malignant bone-forming mesenchymal neoplasm, predominantly affecting adolescents and young adults. "Previous studies reported that suppression of TPP1 caused telomere dysfunction and enhanced radiation sensitivity in a telomerase‐negative osteosarcoma cell line." (PMID 32735728, 2020).
Pancytopenia (1 paper, 2021). An abnormal reduction in numbers of all blood cell types (red blood cells, white blood cells, and platelets). "In contrast, profound progressive pancytopenia was observed in the majority of mice reconstituted with HSCs expressing EGFP only, or EGFP and L191A/L193A, Y376A/Y378A, and R393A/L394A TPP1 mutants." (PMID 33822766, 2021).
preeclampsia (1 paper, 2022). Preeclampsia is a hypertensive disorder of pregnancy that is characterized by new-onset hypertension with proteinuria presenting after 20 weeks of gestation, and depending on mild or severe forms may initially present with severe headache, visual disturbances, and hyperreflexia. "A recent proteomics study of human placental tissue has identified that tripeptidyl peptidase 1 (TPP1) production is reduced in the placenta in early-onset preeclampsia compared to uncomplicated pregnancy." (PMID 36147632, 2022). "Although the localization and function of TPP1 in human placenta have not been determined, a recent proteomics analysis of human placental tissue has identified reduced TPP1 expression in the placenta in early-onset preeclampsia compared to uncomplicated pregnancy." (PMID 36147632, 2022).
prostate carcinoma (1 paper, 2022). A carcinoma that arises from epithelial cells of the prostate gland. "In our study, we develop and validate a prognostic signature (named TILTregSig) composed of five Treg-specific mRNAs (SOCS2, EGR1, RRM2, TPP1, and C11orf54) for prostate cancer, which is associated with RFS in prostate cancer." (PMID 35812443, 2022). "The results demonstrate that the EGR1 exhibited the highest mutation frequency followed by RRM2 and TPP1, while both SOCS2 and C11or54 do not show any mutations in prostate cancer samples." (PMID 35812443, 2022). "However, there has been no study that reported the potential function of TPP1 or C11orf54 in prostate cancer." (PMID 35812443, 2022).
renal carcinoma (1 paper, 2024). A carcinoma arising from the epithelium of the renal parenchyma or the renal pelvis. "Shelterin expression predicted patient survival in 24 cancer types, with TERF1, TERF2, TINF2, and POT1 significantly expressed in testicular, AML, prostate, breast and renal cancers, respectively, and TPP1 in AML and skin cancer." (PMID 39578854, 2024).
telomere syndrome (1 paper, 2016). Accelerated aging syndromes often caused by inheritable gene mutations resulting in decreased telomere lengths. "The majority of the TINF2 mutations found in telomere syndrome patients lie in a cluster outside the binding regions of TINF2 to shelterin proteins TRF1, TRF2, and TPP1 and do not seem to influence the interaction of TINF2 with these proteins." (PMID 27088026, 2016).
testicular cancer (1 paper, 2024). A primary or metastatic malignant neoplasm that affects the testis. "Except for TINF2 in lung and testicular cancers and TPP1 in uterine cancers, shelterin proteins correlate positively across all 40 cancer types analyzed." (PMID 39578854, 2024).
uveitis (1 paper, 2024). An inflammatory process affecting a part of or the entire uvea. "In our study, a careful slit lamp examination at each examination under anaesthesia did not detect any evidence of uveitis in human patients, suggesting that the inflammation seen in the canine model may be related to the use of xenogeneic (human) TPP-1 in the canine study." (PMID 38049626, 2024).
viral infection (1 paper, 2019). "Whether the miRNA181a/Sirt1 axis plays a role in TPP1 posttranscriptional regulation and whether TRF2/TIN2/TPP1 fails to recruit telomerase at telomeres during viral infection is under investigation in our laboratory." (PMID 31191531, 2019).
cancer (28 papers, 2013 to 2025). A tumor composed of atypical neoplastic, often pleomorphic cells that invade other tissues. "Unlike the other shelterin proteins discussed earlier, rare deleterious mutations have been detected in TPP1 that were linked to a predisposition to cancer." (PMID 33599797, 2021). "TPP1 depletion in cancer cells caused DNA damage response at telomeres and led to telomere dysfunction." (PMID 31350723, 2020). "Several mutations in TPP1 gene have been found that are coupled with many diseases including cancer." (PMID 32033110, 2020). "TEL patch mutation of TPP1 suppresses telomerase recruitment and induce cell cycle arrest or apoptosis in certain cancer cells." (PMID 31350723, 2020). "It has been demonstrated that TPP1 is abnormally overexpressed in a variety of malignant tumors and promotes tumor cell migration by regulating telomere stability, DNA damage repair, and the activity of signaling pathways." (PMID 41338460, 2025). "We also performed an exploratory analysis of the expression difference of the TPP1 gene in other cancer types and their corresponding controls using the Oncomine database." (PMID 38722833, 2024). "TPP1's unique status as the only shelterin protein with 22 different glycosylation sites across various cancers highlights its potential significance in cancer biology." (PMID 39578854, 2024). "The dysregulation of TPP1/POT1 can lead to either aberrant telomere elongation or excessive shortening, both of which are implicated in cancer development." (PMID 39012375, 2024). "This is important because the variations in glycosylated TPP1 can be a significant factor while designing cancer therapeutics against TPP1 for different cancers." (PMID 39578854, 2024). "Our study provides a structural basis for the design of TPP1-targeting ligands with therapeutic potential against cancer and telomeropathies." (PMID 37935941, 2023). "Cancers that were found to overexpress TPP1 were reported to have increased telomere length and were associated with more aggressive disease with poorer prognosis." (PMID 33599797, 2021). "RT–PCR, western blotting, and the CCK8 assay confirmed that MYO5A, PLTP, and TPP1 exhibited higher expression in GC tissue and were involved in promoting GC cancer cell proliferation." (PMID 32735728, 2020). "As telomere maintenance element, telosome (telomere sheltering complex protein) is a complex of 6 proteins (TRF1, TRF2, RAP1, TIN2, TPP1 and POT1) which modulation is one of the ways to promote telomere dysfunction associated to cancer high radiosensitivity." (PMID 30405890, 2018). "It was reported that TRF1 and TRF2 are ten times as abundant as TPP1 in several cancer cell lines, and as such it is possible that the different distributions were caused by a mass effect." (PMID 24558398, 2014). "Significantly reduced levels of HSP90β and TPP1 in our study led to an increase in misfolded proteins and the formation of abnormal aggregates, which are the main hallmarks of many diseases, including degenerative diseases and cancer." (PMID 39840062, 2024). "A total of 64.7% (101/156) of cancer patients had co-high expression of both TPP1 and hTERT." (PMID 38722833, 2024). "Overexpressed TPP1 might promote tumor malignancy in specific cancers, implying the possibility of TPP1 being a prognostic predictor of these cancers with high TPP1 expression." (PMID 38722833, 2024). "In this case, TEL-patch targeting ligands might inhibit TPP1-telomerase binding and induce cancer cell senescence." (PMID 37935941, 2023). "Furthermore, TERT promoter mutations cooperate with TPP1 promoter nucleotide changes to lengthen telomeres and with mutated BRAF and FGFR3 oncoproteins to enhance oncogenic signalling in cancer cells." (PMID 38033865, 2023).
cancer (continued). "Telomeric ends are protected by shelterin complexes, which are composed of six proteins, including TRF1, TRF2, RAP1, POT1, TIN2, and TPP1, and their lengths are maintained by telomerase activity regulated by the complexes, depending on cell type (cancer cells and normal cells)." (PMID 35805162, 2022). "The downregulation of TPP1, as observed in some human malignancies, could therefore indirectly elicit chromosomal instability and promote the development of cancer." (PMID 33599797, 2021). "TPP1 is one of the radioresistance proteins because it is overexpressed in the radioresistant cancer cells and its ectopic expression confers radioresistance ability to cancer cell." (PMID 30405890, 2018). "TIFs imply DDR of uncapped telomeres.Recent studies demonstrated that TPP1 involves in DNA damage response and suppression of TPP1 expression in mouse embryo fibroblasts (MEFs) or human cancer cells could initiate telomere dysfunction." (PMID 24260532, 2013). "The modification of TPP1 through glycosylation likely plays a critical role in telomere maintenance, protein stability, cellular localization, and the aggressive characteristics of cancer cells, making it a promising focus for further research and therapeutic development." (PMID 39578854, 2024). "Interestingly, recurrent somatic mutations in the OB-fold domains of POT1 reported causing telomere dysfunction in CLL signifying that alteration of TPP1-telomere binding could lead to genomic instability and cancer." (PMID 32033110, 2020). "Moreover, we observed that TPP1 expression was elevated in radioresistant cells and TPP1 may involve in cancer radioresistance." (PMID 24260532, 2013). "Further analysis reveal that EGR1, TPP1, and SOCS2 confer drug resistance, while RRM2 and C11orf54 exhibit drug sensitivity in pan-cancers." (PMID 35812443, 2022). "The shelterin complex consists of six proteins, termed TRF1, TRF2, RAP1, TPP1, POT1, and TIN2, and abnormal expression of shelterin has been observed in various types of cancers." (PMID 35757510, 2022). "In detail, EGR1, TPP1, and SOCS2 conferred drug resistance, while RRM2 and C11orf54 exhibited drug sensitivity in pan-cancers." (PMID 35812443, 2022). "TPP1 heterodimerizes with POT1 but there are no results about the correlation between TPP1 levels and telomere length in cancer samples." (PMID 24260532, 2013). "Additionally, we show that storage pathology is co-occurring with alterations in the levels of lysosomal enzymes, such as TPP1 and CTSD, which have been described in various pathological conditions such as neurodegenerative lysosomal storage disorders, inflammation, cancer and aging." (PMID 31888773, 2019). "Our data suggest that uncontrolled DNA replication may lead to carcinomas in cells without TPP1." (PMID 38344410, 2024).
tumor (20 papers, 2014 to 2026). "In conclusion, this study demonstrates that a high expression of MYO5A, PLTP, or TPP1 is associated with tumor progress and poor prognosis in GC patients." (PMID 32735728, 2020). "As the shelterin disruption by TPP1 removal from clara cells demonstrated metabolic telomere dysfunction, polymorphisms in DNA damage repair genes, and telomere dysfunction, tumor proliferative markers such as proliferating cell nuclear antigen (PCNA) and Ki67 were assessed." (PMID 38344410, 2024). "TPP1 has been associated with osteoclast degradation of bone, localised in the invasive front of tumours, positively correlated with breast cancer biomarkers cathepsin G, estrogen and progesterone receptors and increased in other cancers such as thyroid adenocarcinoma and liver cancer." (PMID 33317560, 2020). "TPP-1 is a linear PD-L1-binding peptide with a reported affinity of approximately 95 nM and reduces tumor growth by about 56% in H460 xenografts." (PMID 41373467, 2025). "Through external validation using GSE268238, we confirmed that TPP1 was highly expressed in macrophages from tumor tissues." (PMID 40620715, 2025). "Data from TCGA were used to explore the expression differences of NPC2, LY96, and TPP1 at the overall tumor level." (PMID 40620715, 2025). "Lastly, using immunofluorescence, we verified the high expression of TPP1 in the macrophages of tumor tissue." (PMID 40620715, 2025). "TPP1, as a core component of the telomere complex, performs a critical function in tumor developments." (PMID 41338460, 2025). "High expression of TPP1 in tumor cells can protect the telomere end structure from fusion and DNA damage and thus enhance genomic stability and improve cellular immortalization potential." (PMID 38722833, 2024). "They showed superior targeting capacities with TPP1 peptide being delivered and released to the tumor microenvironment through the homotypic effect of tumor cell membrane and specific digestion by the tumor-specific enzyme MMP2." (PMID 36678868, 2023). "The TPP1 peptide was delivered and released into the tumor micro-environment, showing a promising tumor treatment platform." (PMID 34835553, 2021). "RT–PCR confirmed higher expression of MYO5A, PLTP, PALM2‐AKAP2, and TPP1 in tumor tissue than in normal tissue specimens." (PMID 32735728, 2020). "Western blotting confirmed that protein expression of MYO5A, PLTP, and TPP1 was higher in tumor tissue than in normal tissue specimens." (PMID 32735728, 2020). "Immunohistochemistry studies report TPP1 localized mainly in the invasive front of tumours where it acts as a matrix protease." (PMID 33317560, 2020). "Some studies indicated that tripeptidyl peptidase 1 (TPP1) can inhibit tumor growth by interacting with PD-1/PD-L1." (PMID 31798630, 2019). "NPC2, LY96, and TPP1, highly expressed in TAMs, were implicated in promoting tumor growth and immune escape, offering potential targets for novel therapeutic interventions." (PMID 40620715, 2025). "Ultimately, we found that NPC2, LY96, and TPP1 are highly expressed in tumor tissues." (PMID 40620715, 2025). "Indeed, the categorization of macrophages according to NPC2, LY96, and TPP1 expression highlighted their differential impact on the tumor microenvironment." (PMID 40620715, 2025). "Telomerase of tumor cells might be highly activated when both TPP1 and hTERT were overexpressed, which could further result in higher invasiveness and poorer prognosis." (PMID 38722833, 2024).
tumor (continued). "TPP-1 could not only block the PD-1/PD-L1 interaction, as determined by both ELISA and cell-based blocking assays, but could efficiently inhibit tumor growth mediated by T cell reactivation in a tumor xenograft mouse model." (PMID 38915766, 2024). "SPIO NP@M could effectively prolong the half-life of TPP1 peptide and has the ability to reactivate T cells and suppresses tumor development, exhibiting an array of merits including low toxicity, directed release and prolonged in vivo circulation." (PMID 37575228, 2023). "Among the shelterin components, TPP1 showed the strongest correlation with TERT, and its expression increased with tumor multiplicity and advancing stage." (PMID 41751263, 2026). "In a resembling manner, TPP1 positive macrophages secrete MIF acting on T cells, thus inhibiting T cell activity and mediating tumor immune escape." (PMID 40620715, 2025). "Similar to the previous findings, TPP1 positive macrophages secrete TNF and TGFB1 acting on tumor cells, thereby enhancing the proliferation of tumor cells." (PMID 40620715, 2025). "Cell communication analysis revealed increased interaction in tumor tissues, especially involving NPC2, LY96, and TPP1 positive macrophages, which facilitated tumorigenesis and immune evasion." (PMID 40620715, 2025). "Through the specific action of both TPP1 and PLGLLG peptides, SPIO NP@M was delivered and released into the tumor microenvironment narratively." (PMID 37575228, 2023). "The purpose of inhibiting tumor growth was achieved by homotypic targeting of the H460 cell membrane and specific digestion by the MMP2 enzyme, delivering and releasing the TPP-1 peptide that inhibited PD-L1 and PD-1 binding into the tumor microenvironment." (PMID 36005653, 2022). "Besides affinity maturation, other methods such as tetramerization (for 64Cu- and 18F-labeled TPP-1) and dimerization (for 64Cu- and 68Ga-labeled HKP2202) have led to improved tumor uptake and biodistribution." (PMID 38915766, 2024). "Interestingly, RFX5 mRNA has previously been shown overexpressed in HCC compared with non-tumor tissue, which promoted HCC progression via transcriptionally activating KDM4A, TPP1 and YWHAQ." (PMID 37008925, 2023).
neurodegenerative disease (18 papers, 2018 to 2025). A disorder of the central nervous system characterized by gradual and progressive loss of neural tissue and neurologic function. "CLN2 is an autosomal recessive, pediatric neurodegenerative disease that is characterised by deficiency of the lysosomal serine protease tripeptidyl peptidase-1 (TPP1) caused by mutations in the CLN2 gene." (PMID 39595427, 2024). "CLN2 is a pediatric neurodegenerative disease resulting from TPP1 deficiency, leading to increased lysosomal storage material that may cause a progressive decline in motor and language functions." (PMID 33066423, 2020). "Similar to several other neurodegenerative diseases, evidence ofinflammasome activation through Nlpr3 expression was detected inthe Tpp1–/– mouse brain, including transcriptional upregulation of key components ofthat multimolecular signaling complex (i.e., Aim2,Pycard, Naip members, andPanx1)." (PMID 31003587, 2019).
infection (9 papers, 2017 to 2024). The state of being infected such as from the introduction of a foreign agent such as serum, vaccine, antigenic substance or organism. "Considering that both TRF1 and TRF2 are docking sites for other shelterin proteins, it is expected that Rap1, TIN2 and TPP1 are likely to be recruited at VRC during infection." (PMID 32320442, 2020). "Interestingly, the level of genes encoding peptidases (Tpp1, Tpp2, Nrd1, Erap1), which are known to be required for the generation of most MHC class I-binding peptides, were decreased after infection." (PMID 36318581, 2022). "We co-expressed TRF2, TIN2, TPP1, and POT1 by simultaneous infection of cells with individual shelterin baculoviruses." (PMID 29057866, 2017). "Heterogeneous nuclear ribonucleoprotein D (HNRNPD), epsin 2 (EPN2), and tripeptidyl peptidase 1 (TPP1), among others, showed reduced protein levels when cotransfected with CTSW compared to their levels in the green fluorescent protein (GFP) control, regardless of infection." (PMID 35867415, 2022).
neurological disease (5 papers, 2018 to 2023). "Timely classification and public reporting of TPP1 variants is essential as molecular testing increases in use as a first‐line diagnostic test for pediatric‐onset neurological disease." (PMID 31283065, 2019). "Even though the precise functional roles of the downregulated biomarkers in CLN2 disease subjects’ CSF is yet unclear, their identities have previously been associated with neurological disorders and thus may offer insight into TPP1 deficiency as a metabolic disease." (PMID 30323181, 2018).
retinopathy (4 papers, 2018 to 2024). "The ERG data in this case series show CLN2 retinopathy is an early cone/rod disease which is an important distinction from the dachshund TPP1-null canine model that shows an electronegative rod/cone phenotype." (PMID 34272513, 2021).